CD1A (CD1a molecule)
Diseases named in the same sentence as CD1A in open-access papers (continued):
Sharing a sentence is not in itself a finding about the gene and the disease.
Langerhans cell histiocytosis (continued). "Langerhans cell histiocytosis was also considered, but lack of CD1a positivity and Birbeck granules, together with the systemic features in our patient, favored H syndrome." (PMID 41531690, 2026). "Langerhans cell histiocytosis was excluded due to the absence of langerin and strong CD1a expression, while angiolymphoid hyperplasia with eosinophilia was ruled out by the lack of lymphoid follicles." (PMID 41466924, 2025). "Immunohistochemistry aids in distinguishing RDD from other histiocytic disorders; RDD cells are typically positive for S-100 and CD68 and negative for CD1a, unlike Langerhans cell histiocytosis." (PMID 40656404, 2025). "Additional histochemical analysis excluded Langerhans cell histiocytosis (negative CD1a and S100 staining) and malakoplakia (absence of Michaelis–Gutmann bodies)." (PMID 40183740, 2025). "Langerhans cell histiocytosis (LCH), previously known as histiocytosis X, is a relatively uncommon condition characterized by the proliferation of myeloid dendritic cells expressing CD1a, the same antigen expressed in Langerhans cells in the skin." (PMID 41427451, 2025). "Immunohistochemistry further supports its reactive nature, with positivity for CD68 and CD163 indicating macrophage activity, while the absence of langerin and strong CD1a expression helped rule out Langerhans cell histiocytosis." (PMID 41466924, 2025). "Langerhans cell histiocytosis (LCH) is a rare myeloid neoplasm characterized by inflammatory lesions featuring pathological clonal infiltration of cells belonging to the mononuclear phagocyte system, which exhibit phenotypical traits resembling Langerhans cells, notably expressing CD1a and CD207." (PMID 39190425, 2024). "Xanthomas exhibit diffuse strong positive staining for CD 68 and are uniformly negative for S-100 and CD1a, in contrast to Langerhan’s cell histiocytosis, which is positive for S-100 and CD1a." (PMID 38711147, 2024). "Off-label, some of them (vemurafenib, dabrafenib, trametinib, and cobimetinib) can be used in Langerhans cell histiocytosis (LCH) in children with the BRAFV600E mutation, a rare disease characterized by abnormal macrophage proliferation and granulomatous lesions composed of CD1a+CD207+ histiocytes." (PMID 38276485, 2023). "Positive staining of the S-100 protein can help distinguish RDD from granulomatous diseases, and negative expression of CD1a protein rules out the possibility of Langerhans cell histiocytosis." (PMID 36408161, 2022). "Langerhans cells histiocytosis (LCH) was excluded since immunohistochemical evaluation of bone marrow for CD1a and S100 expression was negative." (PMID 36096831, 2022). "Should one remain concerned about non-histiocytic neoplasia, a negative S100 immunostain essentially excludes granular cell tumor, whereas CD1a, S100, and langerin can be employed to exclude Langerhans cell histiocytosis." (PMID 32709245, 2020). "S100, CD1a, Langerin are negative, thereby distinguishing the condition from Langerhans cell histiocytosis." (PMID 32532290, 2020). "ECD cells express the histiocyte marker CD68, CD163, and Factor XIIIa but unlike Langerhans cell histiocytosis do not express CD1a or S100." (PMID 27840753, 2016). "Histopathology confirmed xanthogranulomatous infiltration with foamy histiocytes and Touton giant cells, with immunohistochemistry showing CD68-positive, CD163-positive, CD1a-negative, and S100-negative cells lacking Birbeck granules, consistent with non-Langerhans cell histiocytosis." (PMID 42256999, 2026). "CD1a and Langerin were negative, ruling out Langerhans cell histiocytosis." (PMID 40428260, 2025). "Langerhans cell histiocytosis, though capable of producing ulcerative skin lesions in children, typically presents at a younger age and is characterized by histiocytes with grooved nuclei and positive CD1a or Langerin staining, which were absent in this case." (PMID 40747164, 2025). "Negative CD1a can be distinguished from Langerhans cell histiocytosis." (PMID 39839789, 2024).
Langerhans cell histiocytosis (continued). "Langerhans cell histiocytosis was ruled out by immunohistochemistry (negativity for CD1a)." (PMID 39068468, 2024). "There is a positive immunohistochemistry for the S-100 protein and CD68 marker in RDD, and a negative immunohistochemistry for CD1a, which should be distinguished from lymphoplasmacytic meningioma, plasma cell granuloma, Langerhans cell histiocytosis and Hodgkin lymphoma." (PMID 36596083, 2022). "Diagnosis of ECD requires typing of histiocytes in tissues: these are typically foamy and CD68+ CD1a− in ECD, whereas in Langerhans cell histiocytosis (LCH), they are CD68+ CD1a+." (PMID 34360745, 2021). "In the last decade, the gain-of-function BRAFV600E mutation was observed to be recurrent in the histiocytic disorders Langerhans cell histiocytosis (LCH) and Erdheim-Chester disease (ECD), characterized by the infiltration of CD1a+CD207+ and CD68+CD1a− clonal mononuclear phagocytes, respectively." (PMID 37673974, 2023). "These histiocytes are positive for S100 and CD68 and negative for CD1a, helping distinguish RDD from other histiocytoses, particularly Langerhans cell histiocytosis." (PMID 40351906, 2025). "While unless simultaneous involvement of Langerhans cell histiocytosis (LCH) is present, they should be negative for CD1a." (PMID 35844342, 2022). "Erdheim Chester disease (ECD) is a rare, non-Langerhans cell histiocytosis characterized by widespread tissue infiltration by CD68-positive, CD1a-negative foamy histiocytes." (PMID 30474563, 2018). "Rosai–Dorfman disease (RDD) is a rare form of non-Langerhans cell histiocytosis (non-LCH) that is characterized by the accumulation of large pale CD68+, S100+, and CD1a− histiocytes in various tissues and organs with a spectrum of clinical manifestations." (PMID 38769536, 2024). "Importantly, RDD histiocytes show negative staining for CD1a and CD207, which distinguishes RDD from Langerhans cell histiocytosis (LCH)." (PMID 40282877, 2025). "However, CD1a-negative and S100-negative cells can exclude indeterminate cell histiocytosis (ICH) and Langerhans cell histiocytosis (LCH) but they cannot be used to distinguish necrobiotic xanthogranuloma (NXG) and juvenile xanthogranuloma (JXG)." (PMID 39039599, 2024).
psoriasis (33 papers, 2005 to 2025). An autoimmune condition characterized by red, well-delineated plaques with silvery scales that are usually on the extensor surfaces and scalp. "Elevated frequencies of CD1a-reactive T cells have been found in the blood and skin of patients with psoriasis, and imiquimod-induced inflammation is associated with exacerbated disease in a human CD1a transgenic mouse model." (PMID 37267382, 2023). "KLF6, which has been reported to strongly associate with T cell activation in psoriasis, was also found to be expressed at higher levels in CD1a-GAS reactive IL-22-producing T cells." (PMID 37267382, 2023). "CD1a-restricted T cells from blood and/or skin also recognize antigens implicated in the pathogenesis of skin diseases including psoriasis and atopic dermatitis, as well as in wasp and bee venom responses." (PMID 34914694, 2021). "As CD1a-restricted T cells have been implicated in multiple inflammatory skin diseases such as psoriasis, atopic dermatitis and even contact hypersensitivity, this targeted decrease of CD1a expression might be beneficial in these diseases." (PMID 38979427, 2024). "Among these changes the decrease in CD1a expression on moLCs holds promise to selectively dampen inflammation induced by CD1a restricted T cells, which have been implicated as drivers of inflammation in common inflammatory skin conditions such as psoriasis, atopic dermatitis and contact dermatitis." (PMID 38979427, 2024). "Here, we test the hypothesis that Group A streptococcus induces CD1a reactivity, and investigate the underlying mechanisms and relevance to psoriasis, with therapeutic implications." (PMID 37267382, 2023). "Interestingly, in cancer patients with immune-related adverse events (irAE), the development of psoriasis is associated with the loss of epidermal CD1a+ LCs after treatment with immune checkpoint inhibitors (ICI)." (PMID 36556292, 2022). "Aside from its association with LCH, CD1a is also linked with autoimmune skin diseases such as atopic eczema and psoriasis, thus T cells that recognize CD1a may be implicated in the pathology of many disease states, including cancer and autoimmunity." (PMID 34956202, 2021). "While Th-1 cells have long been a hallmark of psoriasis management, recent research has highlighted the prominence of Th17 cells, which are present in the dermis of psoriatic lesions and mediate skin inflammation upon recognition of self-lipid antigens presented by CD1a." (PMID 39450106, 2024). "What type of phospholipase A2 (PLA2) was shown to ­contribute to psoriasis development in a CD1a-dependent manner?" (PMID 38173286, 2024). "We overview the structure and role of CD1a and outline the current evidence implicating CD1a in the development of psoriasis, atopic dermatitis and allergic contact dermatitis." (PMID 38173286, 2024). "In the context of psoriasis (Ps), CD1a+ LCs (Human Leukocyte Antigen – DR isotype, HLA-DR+), CD1a–DCs (HLA-DR+), and KCs (HLA-DR+), are all APCs that contribute to the pathogenesis of the disease." (PMID 39769151, 2024). "CD1a+ cells play an important role in antigen presentation in psoriasis, but further research into their role is needed." (PMID 38892277, 2024). "In this review, we overview the structure and role of CD1a and outline the current evidence implicating CD1a in the development of psoriasis, atopic dermatitis and allergic contact dermatitis." (PMID 38173286, 2024). "Next, we compared the phenotypes of IFNγ-producing or IL-22-producing CD1a-reactive T cells from healthy and psoriasis." (PMID 37267382, 2023). "Patients with psoriasis had significantly elevated frequencies of IL-22 producing circulating GAS-responsive CD1a-reactive T cells." (PMID 37267382, 2023). "Overall, these data show that individuals with psoriasis have higher frequencies of activated GAS-responsive CD1a-reactive T cells." (PMID 37267382, 2023).
psoriasis (continued). "Circulating AOAH‐responsive CD1a‐reactive T cells from patients with psoriasis showed elevated IL‐22 production." (PMID 34913478, 2022). "Individuals with psoriasis had elevated IL‐22 production by AOAH‐responsive circulating CD1a‐reactive T cells." (PMID 34913478, 2022). "CD1a‐autoreactive T cells from psoriasis patients showed elevated IL‐22 expression in the presence of AOAH, which was enriched in psoriatic lesions." (PMID 34913478, 2022). "CD1a‐autoreactive T cells are elevated in the blood and skin of patients with psoriasis and lipid antigens for CD1a‐autoreactive T cells, can be generated by degradation of the ubiquitous membrane phospholipid, PLA2 through hydrolysis of sn‐2 acyl bond." (PMID 34913478, 2022). "CD1a is constitutively expressed at high levels on LCs which has altered function and migratory patterns in psoriasis." (PMID 34913478, 2022). "In this study, we used immunofluorescence of skin and ELISpot analyses of CD1a‐reactive T cells to investigate the role of the lipase acyloxyacyl hydrolase (AOAH) in CD1a ligand generation with relevance to the pathogenesis of psoriasis." (PMID 34913478, 2022). "Activation of circulating CD1a‐reactive polyclonal T cells from both healthy volunteers and patients with psoriasis was consistent, when cocultured with CD1a‐K562s pulsed overnight with rAOAH." (PMID 34913478, 2022). "We observed significant CD1a-dependent increases in proinflammatory cytokines in CD1a-Tg skin and sera, which overlap with the inflammatory serum profiles of AD and psoriasis patients." (PMID 36477177, 2022). "Autoreactive CD1a-restricted T cells recognize lipid autoantigens in patients with psoriasis, providing a potential link between skin inflammation and CVD." (PMID 33117403, 2020). "Of note, CD1a‐reactive T cells capable of producing IL‐17 and IL‐22 were identified in the blood and skin 69 of psoriasis patients, indicating a potential role for lipid antigens in psoriasis." (PMID 32757303, 2020). "Characterization of LCs in psoriasis lesions was initially performed by immunohistochemistry using markers such as HLA-DR, CD1a, and s100 proteins." (PMID 29520279, 2018). "The presence of CD1a-restricted T cells polarized to IL-17 and IL-22 production in lesional psoriasis is indicative of in situ antigen presentation of LCs to T cells, but formal proof of such events remains to be shown in human settings." (PMID 29520279, 2018). "In another study, urushiol, a molecule found in poison ivy and able to bind CD1a, induced CD1a-restricted T cells, which in a mouse model and in psoriasis patients amplified the local inflammation." (PMID 29963057, 2018). "In humans, enumeration of CD1a-autoreactive T cellsex vivo provided evidence for increased cell number in patients with psoriasis." (PMID 29152228, 2017). "Moreover, increased frequencies of exosome-responsive CD1a-reactive T cells were detected in psoriasis lesions." (PMID 38173286, 2024). "With growing evidence to suggest a broad and critical role for CD1a-dependent mechanisms in inflammatory skin disease pathology, we review here the current literature surrounding the role of CD1a in psoriasis, atopic dermatitis (AD) and allergic contact dermatitis (ACD) pathology." (PMID 38173286, 2024). "Here we investigated whether GAS-responsive CD1a-restricted T cells contribute to the pathogenesis of psoriasis." (PMID 37267382, 2023). "Furthermore, we established cutaneous models of GAS infection in a humanized CD1a transgenic mouse model and identified enhanced and prolonged local and systemic inflammation, with resolution through a psoriasis-like phenotype." (PMID 37267382, 2023). "Given the known expression of AOAH in neutrophils and other immune cells, we reasoned that AOAH may be upregulated in psoriatic lesions and sought to explore the role of AOAH and CD1a‐reactive T‐cell responses in the pathogenesis of psoriasis." (PMID 34913478, 2022).
psoriasis (continued). "When CD1a is over-expressed, symptoms of psoriasis are aggravated in the skin." (PMID 36556292, 2022). "Additionally, circulating CD1a-autoreactive T cell frequency increases in psoriasis patients compared to healthy controls." (PMID 30061888, 2018). "Recent studies have suggested a role for human CD1a in psoriasis." (PMID 29152228, 2017). "Interestingly, IL‐22 production was not significantly increased by T cells from healthy volunteers (left), whereas circulating polyclonal T cells from patients with psoriasis showed a significant increase in production of IL‐22 in a CD1a‐dependent manner in response to rAOAH (right)." (PMID 34913478, 2022). "Concurrently, the percentage of CD1a+ cells at day 6 were 89.3 ± 3.8 and 88.9 ± 2.6%, in controls and patients, respectively, demonstrating that there was no impairment in the ability of monocytes obtained from patients with early-onset psoriasis to differentiate into DC-like cells." (PMID 21933242, 2012). "No GzmK was detected in CD56+ (natural killer cells), CD1a+ (Langerhans cells), nor CD11c+ cells (dermal dendritic cells) despite each of these cell populations being elevated in human psoriasis lesions." (PMID 38903528, 2024). "Perhaps of relevance to this study is that the CD1A inflammatory response is mediated by Th17 cells and that in vivo anti-IL17A treatment has been observed to ameliorate skin inflammation in a mouse psoriasis model." (PMID 34673799, 2021). "Similarly, it has been shown that, in psoriasis, the PLA2-induced antigen production results in an increased CD1a-dependent immune response." (PMID 33807663, 2021). "In conclusion, these studies link GAS infection to the CD1a pathway and show that GAS infection promotes proliferation and activation of CD1a-autoreactive T cells, with relevance to post-streptococcal disease including the pathogenesis and treatment of psoriasis." (PMID 37267382, 2023). "CD1a+ dendritic cell hyperplasia (CD1a+ DCH) has been described in children as part of a large number of disorders including scabies, arthropod bite reactions, prurigo, warts, molluscum contagiosum, spongiotic dermatoses, psoriasis, PL, and interface dermatitis." (PMID 34449607, 2021).